H4C3 (H4 clustered histone 3)
Description:
Core component of nucleosome. Nucleosomes wrap and compact DNA into chromatin, limiting DNA accessibility to the cellular machineries which require DNA as a template. Histones thereby play a central role in transcription regulation, DNA repair, DNA replication and chromosomal stability. DNA accessibility is regulated via a complex set of post-translational modifications of histones, also called histone code, and nucleosome remodeling.
Synonyms: H4/G; H4FG; HIST1H4C; dJ221C16.1; TEBIVANED1; TEVANED1
Target class: Other nuclear protein
Gene: Protein-coding gene on chromosome 6 (26,103,933 to 26,104,337, forward strand). Ensembl gene ENSG00000197061.
Subcellular location: Nucleus; Chromosome
Pathways (Reactome):
Gene expression (Transcription): B-WICH complex positively regulates rRNA expression; DNA methylation; ERCC6 (CSB) and EHMT2 (G9a) positively regulate rRNA expression; MLL4 and MLL3 complexes regulate expression of PPARG target genes in adipogenesis and hepatic steatosis; NoRC negatively regulates rRNA expression; PRC2 methylates histones and DNA; RNA Polymerase I Promoter Escape; RNA Polymerase I Promoter Opening; RUNX1 regulates genes involved in megakaryocyte differentiation and platelet function; RUNX1 regulates transcription of genes involved in differentiation of HSCs; Regulation of endogenous retroelements by KRAB-ZFP proteins; Regulation of endogenous retroelements by Piwi-interacting RNAs (piRNAs); Regulation of endogenous retroelements by the Human Silencing Hub (HUSH) complex; SIRT1 negatively regulates rRNA expression; Transcriptional regulation by small RNAs
Chromatin organization: CHD1 and CHD2 subfamily; CHD6, CHD7, CHD8, CHD9 subfamily; ChAHP complex assembly; HATs acetylate histones; HDACs deacetylate histones; HDMs demethylate histones; Interaction of NuRD complexes with transcription factors; NuRD complex assembly; PKMTs methylate histone lysines; RMTs methylate histone arginines
DNA Repair: Cleavage of the damaged purine; Cleavage of the damaged pyrimidine; Nonhomologous End-Joining (NHEJ); Processing of DNA double-strand break ends; Recognition and association of DNA glycosylase with site containing an affected purine; Recognition and association of DNA glycosylase with site containing an affected pyrimidine; Recruitment and ATM-mediated phosphorylation of repair and signaling proteins at DNA double strand breaks
Cell Cycle: Condensation of Prophase Chromosomes; Deposition of new CENPA-containing nucleosomes at the centromere; G2/M DNA damage checkpoint; Inhibition of DNA recombination at telomere; Packaging Of Telomere Ends
Developmental Biology: Activation of anterior HOX genes in hindbrain development during early embryogenesis; Chromatin modifications during the maternal to zygotic transition (MZT); Replacement of protamines by nucleosomes in the male pronucleus
and 20 more pathways
Gene Ontology:
Molecular function: protein binding; RNA binding; structural constituent of chromatin; DNA binding; protein heterodimerization activity
Biological process: negative regulation of megakaryocyte differentiation; nucleosome assembly; chromatin organization; protein localization to CENP-A containing chromatin; telomere organization
Cellular component: CENP-A containing nucleosome; chromosome, telomeric region; extracellular exosome; membrane; nucleoplasm; nucleosome; nucleus; protein-containing complex; extracellular region; chromosome
Genetic constraint (gnomAD): Loss-of-function variants: 10 observed, 5.7 expected, observed/expected ratio (o/e) 1.76, 90% interval 0.99 to 1.96. That is too few expected variants to judge how well the gene tolerates losing a copy. Missense variants: 191 observed, 158.44 expected, observed/expected ratio (o/e) 1.21, 90% interval 1.07 to 1.36. Synonymous variants: 133 observed, 60.48 expected, observed/expected ratio (o/e) 2.2.
Homologues: Orthologues: chimpanzee H4C6 (100% identical), rabbit H4C1 (100% identical). Paralogues in human: H4C1 (100% identical), H4C11 (100% identical), H4C12 (100% identical), H4C13 (100% identical), H4C14 (100% identical), H4C15 (100% identical), H4C16 (100% identical), H4C2 (100% identical), H4C4 (100% identical), H4C5 (100% identical), H4C6 (100% identical), H4C8 (100% identical), and 2 more.
Diseases named in the same sentence as H4C3 in open-access papers:
H4C3 is named in the same sentence as 4 diseases in open-access papers, as found by Europe PMC text mining. Sharing a sentence is not in itself a finding about the gene and the disease.
H4C3 shares sentences with these, for which no sentence is quoted: cognitive disorder (1 paper); migraine disorder (1); neuralgia (1); peripheral neuropathy (1).